RECQL4 (RecQ like helicase 4)
Description:
An ATP-dependent DNA helicase which unwinds dsDNA with a 3'-overhang in a 3'-5' direction. Does not unwind more than 18 bp of dsDNA. May modulate chromosome segregation. The N-terminal domain (residues 1-54) binds DNA Y-shaped DNA better than ss- or dsDNA. The core helicase domain binds ssDNA.
Synonyms: RecQ4
Tractability: PROTAC: ubiquitination databases record sites on it.
Gene: Protein-coding gene on chromosome 8 (144,511,288 to 144,517,845, reverse strand). Ensembl gene ENSG00000160957.
Subcellular location: Cytoplasm; Nucleus
Subcellular location (Human Protein Atlas): Nucleoplasm
Gene Ontology:
Molecular function: 3'-5' DNA helicase activity; bubble DNA binding; DNA/DNA annealing activity; oxidized purine DNA binding; protein binding; telomeric D-loop binding; helicase activity; ATP binding; ATP hydrolysis activity; catalytic activity, acting on DNA; nucleic acid binding
Biological process: DNA replication; telomere maintenance; telomeric D-loop disassembly; DNA repair; DNA recombination
Cellular component: chromosome, telomeric region; cytoplasm; membrane; nucleoplasm; nucleus; chromosome
Genetic constraint (gnomAD): Loss-of-function variants: 161 observed, 120.83 expected, observed/expected ratio (o/e) 1.33, 90% interval 1.17 to 1.52. The synonymous counts are far from expectation, so gnomAD's model fits this gene poorly and the ratio says little. Missense variants: 2,293 observed, 1,604.4 expected, observed/expected ratio (o/e) 1.43, 90% interval 1.38 to 1.48. Synonymous variants: 996 observed, 647.12 expected, observed/expected ratio (o/e) 1.54, 90% interval 1.46 to 1.62.
Gene-disease validity (ClinGen):
ClinGen rates the evidence that RECQL4 causes each of these diseases.
Rothmund-Thomson syndrome (autosomal recessive): Definitive.
congenital heart disease (autosomal dominant): No Known Disease Relationship. A heart disease that is present at birth.
Cancer hallmarks: genome instability and mutations (suppresses); invasion and metastasis (promotes); escaping programmed cell death (promotes)
Homologues: Orthologues: chimpanzee RECQL4 (98% identical), pig RECQL4 (70% identical), guinea pig RECQL4 (67% identical), rat Recql4 (66% identical), mouse Recql4 (66% identical), dog RECQL4 (63% identical), tropical clawed frog recql4 (47% identical), zebrafish recql4 (45% identical), Drosophila melanogaster RecQ4 (34% identical). Paralogues in human: BLM (17% identical), WRN (16% identical), RECQL5 (13% identical), RECQL (12% identical).
Diseases named in the same sentence as RECQL4 in open-access papers:
RECQL4 is named in the same sentence as 133 diseases in open-access papers, as found by Europe PMC text mining. Sharing a sentence is not in itself a finding about the gene and the disease. The quoted sentences say what the papers report.
Rothmund-Thomson syndrome (62 papers, 2006 to 2025). "Rothmund-Thomson syndrome is thought to be due to mutations in RECQL4, with thumb agenesis being one of the numerous phenotypic manifestations." (PMID 39850168, 2024). "Mutation of RecQ protein-like 4 (RECQL4) causes Rothmund-Thomson syndrome, and the STK11/LKB1 gene mutation results in dysfunction of UV-induced DNA damage responses and hyperpigmentation." (PMID 35087618, 2022). "While loss-of-function RECQL4 mutations are found in diseases characterized by developmental defects and cancer, such as Rothmund-Thomson syndrome, over-expression of RECQL4 is also observed in cancer, such as breast cancer." (PMID 36126066, 2022). "Mutations in RECQL4 are associated with three heritable autosomal diseases: Rothmund-Thomson syndrome (RTS type II), Baller-Gerold syndrome (BGS), and RAPADILINO, each characterized by developmental defects, cancer and/or premature aging." (PMID 36126066, 2022). "Inherited mutations in RecQ helicases result in Bloom Syndrome (BLM mutation), Werner Syndrome (WRN mutation), Rothmund-Thomson Syndrome (RECQL4 mutation), and other genetic diseases, including cancer." (PMID 31772289, 2019). "Inherited mutations in RecQ helicases result in several genetic diseases, including Bloom Syndrome (mutations in BLM), Werner Syndrome (mutations in WRN), Rothmund-Thomson Syndrome (mutations in RECQL4), and other diseases, including cancer." (PMID 31772289, 2019). "Hereditary mutations in RECQL4 result in three genetically distinct diseases known as Rothmund-Thomson syndrome, Baller-Gerold syndrome, and RAPADILINO syndrome." (PMID 29998112, 2018). "Defects in human RECQL4 are associated with three autosomal disorders: Rothmund-Thomson Syndrome (RTS), RAPADILINO syndrome, and Baller-Gerold Syndrome26,27." (PMID 29229926, 2017). "Germ-line mutations in RECQL4 are associated with Rothmund-Thomson syndrome, which is linked to the development of several malignancies, including paediatric osteosarcoma." (PMID 24835790, 2014). "While mutational inactivation of WRN and BLM helicases leads to Werner (WS) and Bloom syndromes (BS) respectively, mutations in RecQL4 lead to three autosomal recessive disorders; Rothmund-Thomson syndrome, Baller-Gerold and RAPADILLINO." (PMID 23894508, 2013). "Sgs1 is a RecQ family DNA helicase and a homolog of the human BLM, WRN, and RECQL4 proteins that are mutated in Bloom's, Werner, and Rothmund Thomson syndromes, respectively." (PMID 23271978, 2012). "Such susceptibility to exogenous oxidative stress was also observed in keratoconus corneal fibroblasts and RECQL4-deficient fibroblasts from patients with Rothmund-Thomson syndrome." (PMID 22065933, 2011). "Unlike BLM and WRN, which are linked to specific diseases with similar symptom clusters, mutations of the RECQL4 gene can lead to a variety of conditions, including Rothmund-Thomson syndrome (RTS), Baller-Gerold syndrome (BGS), and RAPADILINO syndrome, depending on the specific mutation involved." (PMID 40728512, 2025). "Rothmund-Thomson syndrome results from loss of functional RECQL4 or ANAPC1." (PMID 35359366, 2022). "The discovery of the WRN gene has highlighted the human RecQ homologs, RecQL4 and RecQL5, and has led to the identification of Rothmund-Thomson syndrome as a RecQ disease, leading to the idea of an association between chromosomal instability and premature aging." (PMID 36292687, 2022). "The RTS-II patients herein described well summarize the remarkable clinical breadth of Rothmund-Thomson syndrome including mild as well as severe phenotypes at high risk for tumor development, primarily dependent on the pathogenic variants at the causative RECQL4 gene." (PMID 29642415, 2018). "Pathogenic mutations on BLM, WRN, and RECQL4 are associated with several pathological conditions, namely Bloom syndrome (BS), Werner syndrome (WS), and Rothmund-Thomson syndrome (RTS)." (PMID 40728512, 2025).
Rothmund-Thomson syndrome (continued). "RECQL4 deficiency is associated with several diseases, including Rothmund-Thomson syndrome (RTS), RAPADILINO syndrome, and Baller-Gerold syndrome (BGS)." (PMID 35935942, 2022). "Last, mutations in RECQL4 have been associated with 3 distinct, albeit overlapping, genetic disorders: Rothmund-Thomson syndrome (RTS), RAPADILINO syndrome, and Baller-Gerold syndrome (BGS)." (PMID 35025765, 2022). "Rothmund-Thomson syndrome (RTS) is caused by mutations in RECQL4, encoding a helicase that participates in DNA replication and repair." (PMID 33512317, 2021). "In 1999 Rothmund-Thomson syndrome (RTS) was shown to be linked to bi-allelic mutations in a third member of the RecQ family, the RECQL4 helicase." (PMID 32120966, 2020). "Recently, biallelic pathogenic variants in the RECQL4 gene were detected (c.1048_1049delAG and c.1391-1G>A), confirming a diagnosis of Rothmund-Thomson syndrome (RTS)." (PMID 28039508, 2017). "Mutations in RECQL4 occur in three human diseases, Rothmund-Thomson syndrome (RTS, OMIM 268400), RAPADILINO syndrome (OMIM 266280) and Baller-Gerold syndrome (BGS, OMIM 218600)." (PMID 23238538, 2012). "RECQL4 is the gene mutated in Rothmund-Thomson syndrome (RTS)." (PMID 40728512, 2025). "Mutations in RecQ protein-like 4 (RECQL4) belonging to the RECQ DNA helicase family, which participate in many aspects of DNA metabolism, cause Rothmund-Thomson syndrome." (PMID 33918445, 2021). "RECQL4 is a member of this family and its mutation results in Rothmund-Thomson syndrome (RTS)." (PMID 31276497, 2019). "In an autosomal recessive setting, each of these genes confers very rare and complex syndromes, namely Werner syndrome (WRN), Bloom syndrome (BLM), and Rothmund-Thomson syndrome or RAPADILINO syndrome (RECQL4)." (PMID 30086788, 2018). "Like Rothmund-Thomson syndrome (RTS) and Baller-Gerold syndrome (BGS), the syndrome is caused by mutations in RECQL4 gene." (PMID 26064716, 2015). "Rothmund Thomson Syndrome (RTS), RAPADILINO Syndrome and Baller-Gerold Syndrome are very rare human syndromes associated with mutations in RECQL4." (PMID 25859855, 2015). "The DNA helicases, BML and RECQL4, are inactivated in cancer prone genetic disorders such as Bloom and Rothmund-Thomson syndromes." (PMID 25460179, 2014). "Bloom syndrome (BS) confers a very strong predisposition to a wide range of neoplasms, while in Rothmund-Thomson syndrome (RTS) and related cancer predisposition syndromes resulting from RECQL4 mutations the cancer predisposition is largely limited to osteosarcomas and lymphomas." (PMID 23573208, 2013). "CD40L's potential involvement in Immunodeficiency and hyper-IgM, RECQL4's associations with Baller-Gerold syndrome, RAPADILINO syndrome, and Rothmund-Thomson syndrome, and IL7RA's connection to severe combined immunodeficiency exemplify the intricate genetic landscape." (PMID 38890201, 2024). "We cloned RecQL4 and RecQL5 based on the expressed sequence tag (EST) sequences homologous to these three human RecQ-like genes and identified a mutation in the RecQL4 gene in a Rothmund-Thomson syndrome patient." (PMID 36292687, 2022). "Additionally, we found a frameshift mutation in RECQL4, a gene involved in three recessive syndromes with overlapping features, the Rothmund-Thomson syndrome (RTS; OMIM #268400), the Baller-Gerold syndrome (BGS; OMIM #218600), and the RAPADILINO syndrome (OMIM #266280)." (PMID 29659569, 2018). "RECQL4, deficient in Rothmund-Thomson Syndrome, promotes the two major DSB repair pathways, non-homologous end joining (NHEJ) and homologous recombination (HR)." (PMID 29229926, 2017). "Rothmund-Thomson syndrome (RTS) gene product RECQL4 localizes to the nucleolus in response to OS." (PMID 24876913, 2014).
Rothmund-Thomson syndrome (continued). "In humans defects in three of at least five functionally non-redundant genes encoding RecQ helicases are associated with severe heritable disease, i.e. Bloom's syndrome (BLM, RECQ2, RECQL3 gene), Rothmund-Thomson syndrome (RECQL4 gene) and Werner's syndrome (WRN, RECQ3, RECQL2 gene)." (PMID 22327026, 2012). "For example, genes responsible for Werner syndrome (WS), Rothmund-Thomson syndrome (RTS), Bloom syndrome (BS), and Hutchinson-Gilford progeria syndrome (HGPS) are RECQ3 (WRN), RECQL4, RECQ2, and LMNA, respectively." (PMID 25365557, 2014). "The case of the patient with the Rothmund-Thomson syndrome is an example of this fact since RECQL4 is not assayed in the panel." (PMID 36805510, 2023).
osteosarcoma (52 papers, 2010 to 2025). A usually aggressive malignant bone-forming mesenchymal neoplasm, predominantly affecting adolescents and young adults. "Similar DNA helicase aberrations are found in Werner syndrome where the WRN or RECQL4 gene is defective causing melanoma, Osteosarcoma, etc.." (PMID 37081847, 2023). "Rothmund–Thomson syndrome is an autosomal recessive disorder caused by mutations in the RECQL4 gene, which increases cancer risk, particularly osteosarcoma." (PMID 38201628, 2023). "In the autosomal recessive disorder, Rothman-Thomas syndrome, which is associated with skin changes, alopecia, and Osteosarcoma, gene RECQL4 coding for DNA helicase is found to be defective." (PMID 37081847, 2023). "We used U2OS cells since they are commonly used in DNA repair studies and Rothmund-Thomson patients with RECQL4 mutations are predisposed to osteosarcomas." (PMID 36126066, 2022). "A recent case study of five families determined that pathogenic mutation in the helicase domain of RECQL4 is highly associated with osteosarcoma." (PMID 34946868, 2021). "This idea is supported by a recent report that heterozygous germline carriers of pathogenic RECQL4 mutations were over-represented in children with osteosarcoma." (PMID 33541411, 2021). "Although patients with RECQL4 loss of function are predisposed to osteosarcomas, RECQL4 overexpression is also observed in several cancers including breast, cervical, gastric, oral, osteosarcoma, and prostate." (PMID 34946868, 2021). "Genetic diagnosis in RTS is indispensable to confirm the specific subtype and its associated risks: juvenile cataracts are features of RTS1 (ANAPC1 gene), whereas a high risk of osteosarcoma is part of RTS2 (RECQL4 gene)." (PMID 35664819, 2021). "Type 2 RTS patients with biallelic RECQL4 pathogenic variants have multiple skeletal anomalies and a significantly increased incidence of osteosarcoma." (PMID 34965247, 2021). "We then applied an unbiased approach to explore novel molecular mechanisms involved in RECQL4 mutation-induced osteosarcoma to explore therapeutic interventions." (PMID 34965247, 2021). "Germline cancer associations for RECQL4 include osteosarcoma, skin basal cell, and skin squamous cell." (PMID 32508881, 2020). "RECQL4 deficiency in Rothmund–Thomson syndrome leads to an increased incidence of osteosarcoma or lymphoma." (PMID 33014878, 2020). "We describe the cases of two siblings with confirmed germline compound heterozygous RECQL4 mutations and with diagnoses of osteosarcoma." (PMID 33294214, 2020). "RECQL4 has been linked to platinum chemotherapy resistance in gastric cancer, breast cancer and pediatric osteosarcoma." (PMID 33014878, 2020). "Mutations of the RECQL4 gene are associated with the rare type II Rothmund–Thomson syndrome, which has a propensity for osteosarcomas." (PMID 31248416, 2019). "While type I RTS patients are free of RecQL4 mutations, type II patients are often characterized by RecQL4 mutations with an increased risk for osteosarcoma development." (PMID 30206236, 2018). "A strong association has also been found between osteosarcoma and presence of the RECQL4 gene mutation." (PMID 26617641, 2015). "In a study of 18 osteosarcomas, an association was made between overexpression of RECQL4, a gene which encodes a DNA helicase, and S-CIN." (PMID 22685381, 2012). "Loss of RECQL4 function via truncating mutation in individuals with the autosomal recessive familial Rothmund-Thomson syndrome results in significantly higher risk of osteosarcoma, but in sporadic osteosarcoma the rate of RECQL4 mutation is less than 5%." (PMID 22685381, 2012). "Our data are consistent with this in further reaffirming the association of RECQL4 overexpression with osteosarcoma tumorigenesis." (PMID 20465837, 2010). "Heterozygous RECQL4-variants were found to be enriched in paediatric osteosarcoma patients." (PMID 37507557, 2023).
osteosarcoma (continued). "Another of the genetic diseases significantly associated with osteosarcoma involves alterations in RECQL4, which are mainly associated with Rothmund–Thomson syndrome type II; up to 30% of patients with this condition may present with osteosarcomas." (PMID 36499267, 2022). "Mutations in RECQL4 have been associated with low bone mass and osteosarcoma." (PMID 35769265, 2022). "Our findings indicate that mitochondrial respiratory complex I is an “Achilles’ heel” of RTS osteosarcoma and that cancers harboring RECQL4 mutations/deletions, in general, may be vulnerable to mitochondrial respiratory complex I inhibition." (PMID 34965247, 2021). "Suppression of mitochondrial respiratory complex I by OXPHOS inhibitor may offer effective salvage therapies, which currently do not exist for RTS patients as well as for recurrent sporadic osteosarcoma patients with somatic RECQL4 mutations." (PMID 34965247, 2021). "CH variants in RECQL4 have been associated with osteosarcoma in two studies." (PMID 32508881, 2020). "Unfortunately RTS patients with the RECQL4 gene mutation are also at a high risk of developing osteosarcoma, which may also present as a pathologic fracture." (PMID 26617641, 2015). "RECQL4 overexpression is associated with elevated genome instability in osteosarcoma, and genomic instability may, in turn, contribute to chemoresistance and poor prognosis." (PMID 24835790, 2014). "While loss of RecQL4 in RTS patients leads to osteosarcoma due to compromised DNA metabolic activities, gain of expression may favor cancer cell growth and survival through up regulation of DNA replication and repair capabilities." (PMID 23894508, 2013). "Increased incidence of osteosarcoma has been observed in RecQL4 deficient RTS patients." (PMID 23894508, 2013). "Aberrations of the RECQL4 gene (8q24.4) are also associated with osteosarcoma development." (PMID 22685381, 2012). "Genotype-phenotype analysis showed that all patients with the RECQL4 mutation had skeletal abnormalities, further confirming that the RECQL4 mutational status may be indicative of increased risk of osteosarcoma." (PMID 20113479, 2010). "RTS II, on the other hand, is caused by autosomal recessive variants in the RECQL4 gene located at the 8q24.3 locus and is characterized by poikiloderma, congenital bone defects, and an increased risk of osteosarcoma and skin cancers, squamous and basal cell carcinomas." (PMID 35782872, 2022). "This aligns with recent work linking RECQL4 to CXCL12 secretion in osteosarcoma but provides the first evidence of its immunomodulatory function in breast cancer." (PMID 41472745, 2025). "Located on chromosome 8q24.3, RECQL4, a RecQ DNA helicase gene, is often amplified in osteosarcoma, near the MYC gene." (PMID 38201628, 2023). "Tumor growth is diminished when RECQL4 expression is disrupted in osteosarcoma and prostate cancer cells, where RECQL4 is abundantly present." (PMID 37626815, 2023). "The presence of osteosarcoma was seen only in individuals harboring biallelic variants in RECQL4, but given that the individuals in each group are still young, a long-term follow-up is required to determine whether the increased risk for cancer development is restricted to the RECQL4 group." (PMID 38021400, 2023). "Our study has the potential to offer a paradigm shift in the treatment of osteosarcoma in RTS patients and RECQL4-mutated osteosarcoma." (PMID 34965247, 2021). "Because both siblings had osteosarcoma, we gave genetic counseling and sequenced germline RECQL4 genes to test for RTS." (PMID 33294214, 2020). "Loss of RECQL4 protein function occurs in approximately two-thirds of RTS patients and is associated with risk of osteosarcoma." (PMID 32482547, 2020). "Using mouse models of osteosarcoma, we observed delayed cancer formation when Recql4 was also deleted." (PMID 25859855, 2015).